MALAT1 (metastasis associated lung adenocarcinoma transcript 1)
Diseases named in the same sentence as MALAT1 in open-access papers (continued):
Sharing a sentence is not in itself a finding about the gene and the disease.
cancer (continued). "Conversely, the suppression of MALAT1 results in the downregulation of stem cell-associated genes OCT4 and NANOG, leading to the inhibition of cancer cell proliferation and migration and the formation of tumor spheres, while simultaneously promoting cell apoptosis." (PMID 38203269, 2023). "We conducted an examination of MALAT1 expression in cancer tissues obtained from HCC patients." (PMID 37653482, 2023). "Several lncRNAs, such as MALAT1, HOTAIR, PVT1, NEAT1, ANRIL, and SPRY4-IT1, have recently been identified, particularly in cell lines, liquid biopsy, and tissue biopsy samples and have been associated with cancer pathogenesis." (PMID 37424727, 2023). "Previous studies have shown that MALAT1 affected cancer through multiple mechanisms." (PMID 36829256, 2023). "Several studies since then have described MALAT1 function in normal physiology and cancer." (PMID 37370745, 2023). "MALAT1 is a lncRNA that inhibits cell apoptosis and promotes invasion and migration in cancer." (PMID 38203269, 2023). "Taken together, MALAT1 has potential use as a biomarker for cancer diagnosis and prognosis." (PMID 37667226, 2023). "Thus,expression of the MALAT1 transcript is unstable in patientswith different types of cancer and in tumors of different localizations." (PMID 37538803, 2023). "MALAT1 plays a functional role in cancer initiation and progression." (PMID 36605618, 2023). "Metastasis-associated lung adenocarcinoma transcript 1 (MALAT-1) lncRNA was found to sponge miRNAs, which led to a decrease in miR-145 and miR-200, and as a result, the up-regulation of SOX2 for the SRY-Box protein, increasing cancer stem cell properties." (PMID 37444408, 2023). "A unique nuclear expression element is contained in the 3′ end of lncRNA MALAT1, which could protect MALAT1 from degradation and maintain its oncogenic activity in a variety of cancers due to its three-helix structure." (PMID 37927399, 2023). "METTL16 is also important for the maturation of the metastasis-associated lung adenocarcinoma transcript 1 (MALAT1) lncRNA, which may act as either an oncogene or a tumor suppressor depending on the cancer type." (PMID 37612540, 2023). "However, opposite roles for MALAT1 in targeted therapy resistance in other cancers have been described." (PMID 37370745, 2023). "Since its discovery, MALAT1 has become the paradigm of functional alterations of lncRNA in cancer and has been proposed as a potential biomarker with a critical role in several tumors, such as non-small cell lung adenocarcinoma (NSCLC), gastric cancer, and colorectal cancer." (PMID 38068923, 2023). "Yang and colleagues reported that MALAT1 and has-miR-197-3p were both overexpressed in NSCLC tissues and cells when compared with normal tissues, associating them with promoted growth and chemoresistance of cancer." (PMID 36979715, 2023). "Indeed, several studies have shown the beneficial role of MALAT1 downregulation on cancer or metastasis progression in several types of cancer." (PMID 36649031, 2023). "However, to our knowledge, ours is the first study to utilize large-scale TCGA and GTEx datasets to compare MALAT1-expression in these types of cancer and show MALAT1 downregulation in cancerous tissue compared to healthy tissue." (PMID 37235843, 2023). "However, each KEGG pathway has been reported to be closely related to cancer development, indicating the need for further research on MALAT1." (PMID 37667226, 2023). "Accordingly, MALAT1 is considered as a potential anti-cancer drug target." (PMID 36649031, 2023). "Recent studies have shown that MALAT1 was involved in the cancer stemness." (PMID 36829256, 2023). "We show that MALAT1 is strongly downregulated in these cancer types." (PMID 37235843, 2023). "Elevated MALAT-1 expression has been correlated with poor prognosis in several cancer types." (PMID 38124072, 2023).
cancer (continued). "Therefore,MALAT1 is among the key factors contributing to the regulation of the molecularpathways that lead to phenotypic manifestations of cancer." (PMID 37538803, 2023). "We observed multiple METTL16-dependent sites in the cancer-associated MALAT1 lncRNA, however, A8290 was not methylated in vitro." (PMID 37935679, 2023). "In general, MALAT1 is considered as an oncogene in some cancer settings and therefore small molecules that reduce MALAT1 could be interesting for anti-cancer therapies." (PMID 36649031, 2023). "Although a cancer connection has been established for certain lncRNAs (for example, MALAT1 as a prognostic marker for patient survival in colorectal cancer), it remains unclear what role, if any, the majority of lncRNAs serve in malignant disease." (PMID 36841868, 2023). "For instance, m6A lncRNA MALAT1 could regulate metastasis to control cancer cell proliferation, migration, and apoptosis in many cancers; lncRNA XIST bearing m6A and m5C modifications may act as a tumor suppressor or oncogene in colorectal cancer and leukemia." (PMID 37158958, 2023). "We hypothesized that MALAT1 could also be downregulated in other cancer types that have a regulatory axis in MALAT1/MAPK-signaling." (PMID 37235843, 2023). "Studies of MALAT1 function often focus on the overexpression of the lncRNA in cancer cells." (PMID 37620957, 2023). "CD9, caveolin 1 (CAV1), tumor rejection antigen 1 (gp96), exosomal miRNAs (e.g., miR-486-5p, miR-486-3p, and miR-10b-5p are only secreted by cancer cells) have diagnostic value in HNSCC, and increased expression of HSP90, miR-31, miR-21, and MALAT1 are biomarkers for OSCC." (PMID 37046817, 2023). "It was demonstrated that the role of MALAT1 in cancer metastasis is mainly regulated through EMT." (PMID 37919386, 2023). "In addition, MALAT1 has been shown to post-transcriptionally upregulate ZEB2 in cancer, and ZEB2 was the third most upregulated gene in AML-X." (PMID 37528411, 2023). "Finally, similarly to NEAT1 and MALAT1, aberrant Xist expression has been reported in numerous cancer types where it is mainly found overexpressed and acting as an oncogene by interfering with miRNA regulation." (PMID 37444543, 2023). "Another well‐studied lncRNA, metastasis associated lung adenocarcinoma transcript 1 (MALAT1), is known to play either oncogenic or tumor‐suppressive roles in cancers (Q. Chen, Zhu, & Jin, 2020), inducing affecting cancer cell proliferation, migration, and invasion in vitro and tumor metastasis." (PMID 37042179, 2023). "Moreover, some lncRNA genes have been connected with cancer, such as MALAT1, which is a highly conserved lncRNA that is abundantly expressed in cells, and was initially identified as exhibiting elevated expression in metastatic lung cancer." (PMID 36841868, 2023). "Besides, the growth and lymph node metastasis, the major contributors to cancer-caused death in HNSCC, were dramatically inhibited by targeting MALAT1." (PMID 36813772, 2023). "MALAT1 has also been reported to promote tumorigenesis in several cancers." (PMID 37667226, 2023). "MALAT1 expression was found to fluctuate not only in NSCLC but also in various cancers." (PMID 35954272, 2022). "Administering MALAT1 in exosomes has a potential role in treating cancer." (PMID 36419933, 2022). "In conclusion, the higher expression of lncRNA MALAT1 among resistant cancer types is alarming." (PMID 35281907, 2022). "MALAT1 can act multifaceted roles of oncogenes and tumor suppressors in cancer." (PMID 35656022, 2022). "MALAT1 acts on proliferation, metastasis, cell cycle and drug resistance in these cancer cells." (PMID 35645836, 2022). "According to recent studies, MALAT1 function varies in different tumors, which may act as a tumor suppressor gene or have an oncogenic effect on different cancers." (PMID 35650297, 2022). "MALAT1 operates as an oncogene in multiple cancers characterized by extremely elevated expression." (PMID 36163080, 2022).
cancer (continued). "MALAT1, as a highly conserved lncRNA in mammals, is related to cancer development and progression." (PMID 35433477, 2022). "Indeed, MALAT1 lncRNA has been reported as an onco-lncRNA in various cancer types, such as hepatocarcinoma, colon cancer, and breast cancer." (PMID 35804851, 2022). "Moreover, MALAT1 has itself been shown to promote cancer stem cell characteristics with silencing of MALAT1 linked to reduced EMT and cancer stem cells phenotype, which is in complete agreement with the results that we have presented in our study." (PMID 36059695, 2022). "In addition, the MALAT1 expression level is negatively correlated with the survival rate in cancer patients." (PMID 35546353, 2022). "Similarly, in PCa, MALAT1 shows upregulation during cancer progression and is positively correlated with PSA, Gleason score and tumour stage." (PMID 35159022, 2022). "However, it was recently discovered in cancer research that MALAT1-m6A appeared crucial for the migratory ability of cancer cells, as MALAT1 lacking m6A significantly suppressed the metastatic potential of cancer cells." (PMID 35876969, 2022). "LncRNA MALAT1 enhances tumor proliferation, migration, invasion, and growth of cancer cells." (PMID 35281907, 2022). "The proteins that affect iron death could be further evaluated by administering cancer impact factors to mice following the use of MALAT1 inhibitors simultaneously in controls." (PMID 36419933, 2022). "It is conceivable that in the context of overexpression in cancer, MALAT1 may acquire novel gain‐of‐function activities that lead to transcriptome deregulation and promote cancer progression." (PMID 34668345, 2022). "The potential role of MALAT1 in cancer therapy could be explored by conducting MALAT1 inhibitor experiments in mice followed by the simultaneous application of cancer impact factors in a control group." (PMID 36419933, 2022). "Loss of function assays have demonstrated that the downregulation of Malat1 leads to a similar cancer phenotype, displaying a lower ratio of proliferation and migration and delayed tumor growth accompanied by disruption of actin stress fibers and increasing apoptosis in both tumors." (PMID 35447891, 2022). "Additionally, using a set of methods, the promoting effect of interactomes formed by MALAT1 on the progression of various types of cancer, including increased proliferation, migration, invasion, EMT, and, in contrast, suppression of apoptosis, was established." (PMID 36362406, 2022). "MALAT1 could be the pan-cancer master biomarker regulating these driver genes’ expressions at the transcriptional as well as at post-transcriptional level." (PMID 35534592, 2022). "High expression of MALAT1 is closely related to numerous human cancers." (PMID 35305641, 2022). "Investigating the mechanism of the interaction between MALAT1 and iron death could lead to the development of effective new therapies for various cancers." (PMID 36419933, 2022). "In addition, MALAT1, which lacks m6A modifications, inhibits the metastatic potential of cancer cells." (PMID 35534472, 2022). "METTL3 has been known to upregulate the expression of MALAT1 in several cancer types." (PMID 36212476, 2022). "LncRNA MALAT1 is shown to play role in oncogenesis and cancer development." (PMID 35203705, 2022). "Moreover, the relation of chromatin-associated RNAs with cancer progression has been documented in many instances, such as PVT1, H19, MALAT1, and HOTAIR (for a recent review, see reference 45)." (PMID 36445136, 2022). "Emerging study has shown that MALAT1 can regulate the expression of FBXW8 in human cancer." (PMID 35928868, 2022). "Additionally, MALAT1 affected cancer cell proliferation through its regulation of the MAPK signaling." (PMID 35656022, 2022). "MALAT1 is found to facilitate human cancer and chemoresistance development." (PMID 35609308, 2022). "The roles of MALAT1 in many cancers and chemoresistance have been investigated." (PMID 35609308, 2022).
cancer (continued). "The interaction between differentially expressed lncRNAs, such as MALAT1 and CDKN2B-AS1, and histone-modifying or chromatin-remodeling complexes has been implicated in transcriptional regulation, enabling the progression of different cancer types." (PMID 36313424, 2022). "Although, in healthy adults, sexual organs appear to be the main sources of some of the most widely reported cancer-associated lncRNAs such as PVT1 and MALAT1 that are mostly expressed in the ovaries of healthy women, while PTENP1 is largely expressed in the testis of healthy men." (PMID 35729321, 2022). "Similarly, while MALAT1 has been extensively studied as an oncogenic lncRNA, a recent study suggests that downregulation of MALAT1 results in increased cancer cell migration and correlates with reduced patient survival." (PMID 36010859, 2022). "MALAT1 behaves as an oncogene in the initiation and progression of many cancers." (PMID 34489556, 2022). "In tumor cells, MALAT1 by targeting several transcription factors, growth factors, hormones, and epigenetic histone modifications can mediate cancer cell proliferation, tumorigenicity, autophagy, epithelial-mesenchymal transition (EMT), metastasis, and drug resistance phenotypes." (PMID 35305641, 2022). "Curiously, Malat1 exerts oncogene function by different mechanisms depending on cancer type." (PMID 35447891, 2022). "MALAT1 has been validated to have a role in cancer diagnosis, prognosis and therapy." (PMID 35928868, 2022). "However, future investigations should focus on the sensitivity and specificity of MALAT1 and H19 in cancer detection." (PMID 35052495, 2022). "MALAT1 influences cancer metastasis through induction of epithelial-mesenchymal transition (EMT)." (PMID 36059695, 2022). "miR-124 could reverse the silencing of MALAT1 and the subsequent tumor-suppressor effect in different human cancer xenografts." (PMID 35071748, 2022). "Our results showed that MALAT1 was differently expressed in different kinds of cancers." (PMID 34308750, 2021). "And MALAT1 expression had a worse or better prognosis across different cancers." (PMID 34308750, 2021). "MALAT1 induces cancer cell proliferation, invasion, and migration in mice." (PMID 34457116, 2021). "A meta-analysis revealed that MALAT1 could be a novel biomarker in various cancers, including ovarian." (PMID 34680193, 2021). "MALAT1 RNA could also induce the EMT process in different cancer cells including lung, breast, and colon." (PMID 35178360, 2021). "It is suggested that MALAT1 plays a role in cancer progression and metastasis by enhancing EMT." (PMID 34026626, 2021). "Expression, clinical significance and function of MALAT1 in pan-cancer exist as big difference." (PMID 34308750, 2021). "However, the role of MALAT1 in cancer is controversial, as conflicting studies have shown that it can act as an oncogenic factor or as a tumor suppressor." (PMID 34940760, 2021). "In addition to MALAT1, several other cancer-associated lncRNAs are involved in the regulation of invasion, metastasis and epithelial to mesenchymal transition (EMT) of cancer cells." (PMID 33435206, 2021). "Thus, MALAT1 represents both a promising cancer bio-marker as well as a potential therapeutic target for limiting metastatic growth." (PMID 35145971, 2021). "In recent years, accumulating evidence has shown that the aberrant expression of MALAT1, especially in serum/plasma, may serve as a suitable biomarker in various human cancer entities." (PMID 34527584, 2021). "However, another two databases (Oncomine and TIMER) demonstrated different expression level of MALAT1 in cancers." (PMID 34308750, 2021). "Previously, long noncoding RNA MALAT1 was reported upregulated in GC cells and could positively regulate autophagy in various cancers." (PMID 33824303, 2021).
cancer (continued). "Combined with the negative regulation of miR-188-5p in the progression of other cancers, here, we hypothesized a possible mechanism that miR-188-5p may be involved in the MM cell proliferation and development regulated by MALAT1." (PMID 33944676, 2021). "lncRNAs, such as MALAT1, were reported to play critical roles in a wide variety of biological processes, including cell differentiation/development, disease pathogenesis, immune responses, and especially cancer progression." (PMID 34638541, 2021). "The roles of MALAT1 in tumorigenesis are complicated, as it can function as either a promoter or a suppressor in metastasis depending on the mechanism of action in different cancers." (PMID 34574033, 2021). "In addition, the PrognoScan database was also used to study prognostic significance of MALAT1 in human cancers." (PMID 34308750, 2021). "Lnc-H19 and MALAT1 has been proved to be promising targets for cancer therapy." (PMID 34041287, 2021). "The aim of our study is to explore the role of MALAT1 in different types of cancers." (PMID 34308750, 2021). "All these discoveries emphasize the cancer type-specific role of MALAT1 in tumor development." (PMID 33522932, 2021). "Therefore, identification of regulatory sites targeted by proteins in MALAT1 is crucial for understanding its pathogenesis in cancers." (PMID 33441968, 2021). "Hence, cancer specific expression of MALAT1 can be explored for targeted therapy as well as biomarkers in cancer." (PMID 34303380, 2021). "MALAT1 downregulation also significantly reduced cancer metastasis of Bel7402 cells." (PMID 34001866, 2021). "At the beginning, MALAT1 was found to be a poor prognostic marker for cancer patients." (PMID 34308750, 2021). "Structural changes unique to K562 cells and HeLa cells provide new mechanistic leads into how the structure of MALAT1 may mediate cancer in a cell-type specific manner." (PMID 33450947, 2021). "Therefore, in this study, the data in some public databases were used to comprehensively study the expression and prognostic significance of MALAT1 in cancers." (PMID 34308750, 2021). "LncRNAs like MALAT1 and HOTAIR which are associated with metastasis are over expressed in cancer and MEG3 and PTENP1 which inhibit cell proliferation and migration are downregulated in cancer." (PMID 34858475, 2021). "The lncRNA MALAT1 is involved in cancer development and drug resistance." (PMID 34164906, 2021). "However, the MALAT1 effect on the interaction between stromal and cancer cells have been rarely studied." (PMID 33824303, 2021). "Moreover, different expression levels of MALAT1 in peripheral blood were observed between cancer patients and healthy controls." (PMID 34778078, 2021). "Moreover, MALAT1 has numerous known miRNA- and protein-binding partners, some of which mediate cancer." (PMID 33450947, 2021). "MALAT1 has been proven a potent repressor for cancer cell apoptosis." (PMID 33414433, 2021). "In addition, the expression level of MALAT1 can also be used as a biomarker of chemosensitivity in different cancers." (PMID 34778078, 2021). "Moreover, the lncRNAs HOTAIRM1, PTENP1, and MALAT1 were found to be involved in the activation of autophagy and regulation of several physiological processes and malignant phenotype of cancer cells." (PMID 33850225, 2021). "LncRNAs HOTAIR, MALAT1, MEG3, and H19 are associated with a large number of cancer types." (PMID 34680193, 2021). "Several reports have confirmed that MALAT1 knock‐down could trigger activation of apoptosis in cancer cells." (PMID 34164906, 2021). "A-kinase anchoring protein 9 (AKAP9) is a target gene for the cancer-promoting effect of MALAT1." (PMID 34820188, 2021). "Interestingly, it has been also recently reported that m6A modification of MALAT1 is critical for metastatic ability of cancer cells, reshaping the nuclear speckles." (PMID 34530916, 2021). "UBE2C restoration attenuated the MALAT1 knockdown-induced anti-cancer effects." (PMID 34257576, 2021).